CXCR3 (C-X-C motif chemokine receptor 3)
Diseases named in the same sentence as CXCR3 in open-access papers (continued):
Sharing a sentence is not in itself a finding about the gene and the disease.
neurofibroma (5 papers, 2020 to 2024). An intraneural or extraneural neoplasm arising from nerve tissues and neural sheaths. "CXCR3 expression in inflamed nerves and neurofibromas is localize to T cells and DC." (PMID 36479091, 2022). "Additionally, since macrophages are recruited via CXCL10-CXCR3, which are expressed in T cells and dendritic cells, the deletion of CXCR3 may prevent neurofibroma formation." (PMID 34359780, 2021). "In the neurofibroma TME, Schwann cells recruit T cells and dendritic cells to the sites of neuroinflammation and neurofibroma lesions via the CXCL10/CXCR3 pathway." (PMID 39429695, 2024). "In these neurofibroma-prone mice, global deletion of the CXCL10 receptor CXCR3 prevented neurofibroma development, and anti-CXCR3 antibodies reduced tumor numbers to some extent." (PMID 36479091, 2022). "There have been far fewer studies of CXCR3 in the PNS than in the CNS, with previous PNS-related studies only investigating the role of CXCR3 in neurofibroma, nonneurogenic tumors, and neuroinflammatory pain models based on peripheral neuropathy." (PMID 39429695, 2024).
renal fibrosis (5 papers, 2010 to 2025). A final common manifestation of a wide variety of chronic kidney diseases characterized by glomerulosclerosis and tubulointerstitial fibrosis. "Interestingly, IP-10 neutralization by monoclonal antibody or CXCR3 deficiency in a transgenic mouse model were associated with increased severity of renal fibrosis in a unilateral ureteral obstruction model related with overexpression of TGF-β in kidneys." (PMID 27219334, 2016). "The role of CXCR3 in fibrosis and organ damage seems paradoxical, as CXCR3 is upregulated in cases of progressive renal fibrosis." (PMID 40977717, 2025). "In animal models, inhibition of CXCL10/CXCR3 could result in progressive renal fibrosis by upregulating the expression of TGF-β." (PMID 35281025, 2022). "Thus, overexpression of IP-10 and CXCR3 after UUO seems to serve as a protective mechanism against renal fibrosis." (PMID 20412564, 2010). "Reportedly, sorafenib, an xCT inhibitor, can inhibit the TGF-β/Smad3-induced EMT signaling and suppress the CXCR3/CXCL11-mediated macrophage infiltration, ameliorating renal fibrosis." (PMID 35655759, 2022).
B-cell lymphoma (4 papers, 2017 to 2024). "The role of CXCL10 in B cell lymphomas has not been studied well, but it is known that its receptor CXCR3 is expressed on a small subset of B cells." (PMID 30301877, 2018). "Importantly, the mean expression intensities of CXCR3, as well as LAT1 in CD8 + T cells were highly elevated in MM patients compared to B cell Non-Hodgkin lymphoma and MDS control cohorts, confirming the specific enrichment of aberrant inflammatory CD8 + T cells in MM." (PMID 39613747, 2024).
chronic lung disease (4 papers, 2016 to 2022). According to the definitions of the American and British Thoracic Societies, including pulmonary functional tests, X-rays, and CT scans for items such as fibrosis, bronchiectasis, bullae, emphysema, nodular or lymphomatous abnormalities. "Recent studies showed that CXCR3 exists on mast cells in acute lung injury and chronic lung disease." (PMID 35036436, 2022). "It was generally believed that CXCR3 was not expressed on neutrophils, while recent studies showed that CXCR3 was present on neutrophils in acute lung injury and chronic lung disease." (PMID 28046003, 2017). "Recent studies have shown the expression of CXCR3 on neutrophils from patients with chronic lung disease, but not in healthy control subjects." (PMID 27965774, 2016).
chronic prostatitis (4 papers, 2021 to 2025). An infectious or non-infectious chronic inflammatory process that affects the prostate gland. "Our results indicated CXCL10 as an important mediator involved in inflammatory infiltration and pain symptoms of prostatitis by promoting the migration of macrophages and secretion of inflammatory mediators via CXCR3-mediated ERK and p38 MAPK activation." (PMID 34659199, 2021). "Our previous study showed that serum CXC10 levels were positively associated with symptoms of chronic prostatitis, and the CXCL10/CXCR3 axis could activate the p38 and ERK to induce prostate macrophage migration and cytokine release." (PMID 39718951, 2025). "Because STAT3 was regulated by the JAK, we proposed that the JAK/STAT3 pathway may be downstream of the CXCL10/CXCR3 axis to induce spinal macrophage recruitment and pain in chronic prostatitis." (PMID 39718951, 2025). "CXCL10 was a ligand of CXCR3, which might bind to CXCR3 to attract macrophage infiltration in the spinal cord to induce neuroinflammation and chronic prostatitis pain symptoms." (PMID 39718951, 2025). "Hence, the JAK/STAT3 pathway in spinal macrophage may play an important role in the CXCL10/CXCR3 axis‐induced neuroinflammation and mediate pain response in chronic prostatitis." (PMID 39718951, 2025). "This study demonstrated the important roles of the CXCL10/CXCR3, JAK/STAT3 and NGF/TrKA pathways in neuroinflammation and pain in chronic prostatitis, which provided novel therapeutic targets for pain management in chronic prostatitis." (PMID 39718951, 2025). "However, the relationship between the CXCL10/CXCR3 axis and the JAK/STAT3 pathway in neuroinflammation and pain in chronic prostatitis was unknown." (PMID 39718951, 2025). "Taken together, these findings demonstrated the important roles of the CXCL10/CXCR3 axis in modulating the JAK/STAT3 pathway and inducing neuroinflammation to mediate pain in chronic prostatitis, and targeting the NGF/TrKA pathway showed therapeutic efficacy in pain treatment in chronic prostatitis." (PMID 39718951, 2025).
clear cell renal cell carcinoma (4 papers, 2016 to 2020). "High expression levels of CXCR2 or CXCR3 were found to be associated with patients with advanced stage renal clear cell carcinoma." (PMID 27297979, 2016). "High expression levels of CXCR2 or CXCR3 were found to be significantly associated with the high‐risk group of patients with renal clear cell carcinoma." (PMID 27297979, 2016).
colorectal tumor (4 papers, 2014 to 2023). "In our study, we also observed reduced CTL number in colorectal tumors upon ablation of CXCR3 in hematopoietic cells." (PMID 31775909, 2019). "CXCR3 signaling in hematopoietic cells is dispensable for the recruitment of Th1, Th17, and myeloid cells to colorectal tumors." (PMID 31775909, 2019). "An earlier study stated that the expression of CCR5 and CXCR3 has a positive correlation with the accumulation of CD8+ and CD4+ T lymphocytes in invasive colorectal tumors." (PMID 24565056, 2014). "Indeed, ablation of CXCR3 in all blood cells by means of bone marrow reconstitution resulted in reduced recruitment of CD8+ T cells, and to a lesser extent, Tregs to colorectal tumors." (PMID 31775909, 2019). "Indeed, mice that lack CXCR3 in hematopoietic cells developed increased numbers of colorectal tumors, without changes in tumor sizes." (PMID 31775909, 2019). "Signaling of CXCL9/10 through CXCR3 is required for the recruitment of CD8+ CTLs and Tregs, but not Th1 or Th17 cells, to colorectal tumors." (PMID 31775909, 2019).
cryptococcal infection (4 papers, 2014 to 2025). "A higher proportion of CD8+ T cells coexpressing CCR5 and CXCR3 was found in CSF of patients with cryptococcosis-associated IRIS compared with blood at ART initiation." (PMID 25587282, 2014). "In addition, recruitment of murine pDCs to the lungs during cryptococcal infection requires C-X-C motif chemokine receptor 3 (CXCR3)." (PMID 29543719, 2018). "Following a cryptococcal infection, chemokines such as CCL2, CXCL1, CCL5, and CXCR3 ligands (CXCL9, 10, and 11) were secreted by astrocytes and T cells were recruited into the brain in a CXCR3-dependent manner." (PMID 36294634, 2022).
cystitis (4 papers, 2008 to 2018). Inflammation of the urinary bladder. "CXCR3 blockade at the level of the urinary bladder in intermediate (48 h) cystitis reduced the number NVCs." (PMID 29681802, 2018). "CXCR3 blockade at the level of the urinary bladder in acute (4 h) cystitis reduced the number of NVCs." (PMID 29681802, 2018). "The CXC chemokine family is pro-inflammatory with family members CXCL9, CXCL10, CXCL11, and their common receptor, CXCR3, contributing to urinary bladder inflammation." (PMID 29681802, 2018). "Targeting CXC/CXCR3 signaling at the level of the urinary bladder may be a novel target to improve bladder dysfunction and somatic sensitization following urinary bladder inflammation." (PMID 29681802, 2018). "CXCL9-11 and their common receptor, CXCR3, are thought to contribute to bladder inflammation in BPS/IC patients and preclinical murine models of urinary bladder inflammation." (PMID 29681802, 2018). "Here, to further characterize the inflammatory reaction in HIC, we examined CXCR3 expression of infiltrating immune cells in HIC specimens by immunohistochemistry using non-IC cystitis specimens as a control." (PMID 27339056, 2016). "Meanwhile, the number of CXCR3-positive cells significantly correlated with that of CD20-positive B cells or CD138-positive plasma cells in HIC specimens but not in non-IC cystitis control specimens." (PMID 27339056, 2016). "CYP-induced cystitis in mice led to substantial increases in the expression of CXCL10, CXCL11, and CXCR3 mRNA by urinary bladder leukocytes as well as modest increases in the expression of CXCL9 and CXCR3 transcripts by iliac lymph node lymphocytes than compared to normal, untreated mice." (PMID 18957084, 2008). "Hence, the current study suggests CXCL10 is partially responsible for changes in the distribution of CXCR3+ Th1 cells, mast cells, and NKT cells from the spleen and iliac lymph nodes to the urinary bladder after CYP treatment, which corresponded with cystitis." (PMID 18957084, 2008). "The presence of anti-CXCL10 Ab might hinder the movement of these CXCR3+ T cells that would otherwise migrate to the urinary bladder and/or iliac lymph nodes to exacerbate CYP-induced cystitis." (PMID 18957084, 2008). "The mean sum of proportion of the number of CXCR3-and CD138-positive cells to the number of all mononuclear cells was significantly higher in HIC cases than non-IC cystitis cases, and exceeded 1.0, suggesting the presence of CXCR3-and CD138-double positive cells." (PMID 27339056, 2016). "On the other hand, the distribution of CXCR3-positive cells and CD138-positive plasma cells was poorly matched in non-IC cystitis." (PMID 27339056, 2016). "However, distribution of CXCR3-positivity in plasma cells indicated co-localization of CXCR3 with CD138 in HIC specimens, but not in non-IC cystitis specimens." (PMID 27339056, 2016).
glaucoma (4 papers, 2015 to 2024). Increased pressure in the eyeball due to obstruction of the outflow of aqueous humor. "The loss of retinal neurons in the GCL is a hallmark of glaucoma, and both inflammation and oxidative stress can cause neuronal cell death; therefore, we investigated whether blocking CXCR3 pathway would protect retinal neuronal cells from IOP-induced cell death." (PMID 26448323, 2015). "The CXCR3 pathway plays an important role in the aetiology of glaucoma, with expression levels correlating with the progression of POAG24." (PMID 33414477, 2021). "Additionally, glaucoma was induced in mice with CD4-specific expression of Tomato, and immunofluorescence staining using anti-CXCR3 antibodies demonstrated a significant presence of CXCR3+ CD4+ T cells within the retina." (PMID 38317227, 2024).
Hyperglycemia (4 papers, 2018 to 2025). An increased concentration of glucose in the blood. "Hyperglycemia in neonatal rats can induce CXCL10/CXCR3 signaling, microglial activation, and astrocyte proliferation, altering long‐term synaptic formation and function in the hippocampus." (PMID 40130458, 2025). "Neonatal hyperglycemia induces CXCL10/CXCR3 signaling, microglial activation, and astrocytosis in the rat hippocampus and alters long-term synaptogenesis and behavior." (PMID 29544513, 2018). "Our present study confirms a similar response in the hippocampus and demonstrates the novel finding that hyperglycemia upregulates the CXCL10/CXCR3 signaling pathway." (PMID 29544513, 2018). "In summary, we found that hyperglycemia in newborn rats induces CXCL10/CXCR3 signaling, microglial activation, and astrocytosis, and alters long-term synaptogenesis and function in the hippocampus." (PMID 29544513, 2018). "On P6, the transcript and protein expression of markers of oxidative stress and inflammatory cytokines, including the CXCL10/CXCR3 pathway, were upregulated in the hyperglycemia group." (PMID 29544513, 2018). "Although this pathway is implicated in the pancreatic β cell destruction in T1D and serum CXCL10 is considered a biomarker of T1D in adult humans, to our knowledge, this is the first demonstration of CXCL10/CXCR3 upregulation in the hippocampus due to hyperglycemia." (PMID 29544513, 2018). "Upregulation of these markers in the recurrent hyperglycemia model rules out STZ as the primary cause of CXCL10/CXCR3 upregulation." (PMID 29544513, 2018). "Our findings may align with previous studies showing that hyperglycemia promotes the expression of CXCL10 and CXCL11 on Schwann cells, recruiting CXCR3‐expressing CD8+ lymphocytes and leading to apoptosis of the Schwann cells." (PMID 37021432, 2023). "In addition, hyperglycemia enhances NF-κB signaling pathway—increased NF-κB and its co-activator PARP1 expression—and also promotes the overexpression of CXCL10 by neurons, microglia and astrocytes, and its receptor CXCR3, expressed by neurons and microglia." (PMID 36869375, 2023). "Whether hyperglycemia affects CXCL10/CXCR3 signaling in the developing hippocampus is not known." (PMID 29544513, 2018).
hypersensitivity pneumonitis (4 papers, 2005 to 2024). Hypersensitivity pneumonitis (HP) is a pulmonary disease with symptoms of dyspnea and cough resulting from the inhalation of an antigen to which the subject has been previously sensitized. "Despite indications that the CXCL10/CXCR3 axis is involved in the development of hypersensitivity pneumonitis (HP), nothing is known about the therapeutic benefits of small molecule suppression of the pair components." (PMID 36164329, 2022). "Using immunohistochemical studies of tissue sections and a flow cytometry evaluation of cells recovered from the bronchoalveolar lavage (BAL), we studied the role of CXCR3/CXCL10 interactions in the regulation of T-cell migration into the lung of patients with hypersensitivity pneumonitis." (PMID 15725351, 2005). "Knocking out IFN-γ was demonstrated to prevent C-X-C motif chemokines mobilization, recruitments of CXCR3(+)/CD4(+) T cells into the lung, and eventual alveolitis and granuloma formation." (PMID 36164329, 2022).
injury (4 papers, 2021 to 2024). Damage inflicted on the body as the direct or indirect result of an external force, with or without disruption of structural continuity. "Harnessing CXCR3-guided migration of MSCs offers possibilities to enhance the efficacy of MSC therapy to treat neonates with HI brain injury in the future." (PMID 38715091, 2024). "Interestingly, PALF survivors’ DyNA and DyBN networks exhibit connectivity between MIG and IP-10, and APAP is associated with upregulation of CXCR3, the receptor for both MIG and IP-10 in mouse models of liver injury." (PMID 40809145, 2024). "In the present study, we indicated that single and repeated intrathecal administration of CXCR2 (NVP CXCR2 20) and CXCR3 ((±)-NBI 74330) antagonists resulted in a strong and persistent dose-dependent analgesic effect 7 days after nerve injury in rats." (PMID 34681732, 2021).
Kawasaki disease (4 papers, 2016 to 2022). A rare inflammatory disease characterized by an acute febrile, systemic, self-limiting, medium-vessel vasculitis primarily affecting children. "Based on these theories, reducing the level of IFN-γ and preventing these kinds of CD4 + CXCR3+ T cells from infiltrating the coronary arterial wall may be useful in the treatment of Kawasaki disease and prevention of CALs." (PMID 30704426, 2019). "Our study shows that we can distinguish normal samples from Kawasaki disease samples based on the infiltration of immune cells, and that CXCL8, CCL5, CCR7, CXCR3, and CCR1 may play important roles in the development of Kawasaki disease." (PMID 33188570, 2021).
non-alcoholic steatohepatitis (4 papers, 2022 to 2025). "Our research group has previously demonstrated that DM509 treatment to non-alcoholic steatohepatitis mice decreased liver CXCR3, CXCL9, CXCL10, TNFα, IL-1β, and TGF-β expression." (PMID 38235144, 2023). "CXCR3 can damage liver cell autophagy by inducing lysosomal damage and endoplasmic reticulum stress, and it has an important regulatory role in the development of nonalcoholic steatohepatitis." (PMID 36611975, 2023).
non-small cell lung carcinoma (4 papers, 2012 to 2025). A group of at least three distinct histological types of lung cancer, including non-small cell squamous cell carcinoma, adenocarcinoma, and large cell carcinoma. "Increased CXCR3 expression in tumor nests is associated with prolonged survival and more inflammatory cell infiltration in patients with non-small cell lung cancer (NSCLC)." (PMID 22438899, 2012). "Unlike other cancers, in clinical specimens of non-small cell lung cancer (NSCLC), tumor cells and blood vessels are predominantly negative for CXCR3, while infiltrating immune cells show strong CXCR3 staining." (PMID 40786052, 2025).
organizing pneumonia (4 papers, 2017 to 2022). "They found, in a multivariate adjusted model that higher expression of these CXCR3 chemokine ligands in BAL, in co-presence with organizing pneumonia, led to significantly increased CLAD risk." (PMID 34122421, 2021).
pancreatic ductal adenocarcinoma (4 papers, 2014 to 2023). An infiltrating adenocarcinoma that arises from the epithelial cells of the pancreas. "Talabostat inhibited tumor growth in pancreatic ductal adenocarcinoma models and promoted the infiltration of the tumors by CXCR3+ T and NK cells, most likely by inhibiting DPP-IV." (PMID 35565202, 2022). "We analyzed the expression of CXCR3 by immunohistochemistry in pancreatic ductal adenocarcinoma samples of 30 patients." (PMID 25415223, 2014). "Studies demonstrated that DPP inhibition altered the CXCR3 axis and enhanced NK and CD8+ T-cell infiltration to improve anti-PD1 efficacy in murine models of pancreatic ductal adenocarcinoma." (PMID 37350944, 2023). "In pancreatic ductal adenocarcinoma, CXCL10 has been shown to recruit CD4+, CD8+, and CXCR3+ T cells as well as FOXP3+ Tregs27." (PMID 34504204, 2021).
Splenomegaly (4 papers, 2009 to 2023). Abnormal increased size of the spleen. "The results indicated that CXCR3+, PD-L1+CXCR3+%, and PD-1+CXCR3+ lymphocytes were associated with poor prognostic features such as hepatomegaly, staging, splenomegaly, and recurrence." (PMID 36726488, 2023). "Moreover, CXCR3+% and PD-L1+CXCR3+% associated positively with both splenomegaly (r = 0.348, P = 0.002; r = 0.268, P = 0.018) and general lymphadenopathy (r = 0.362, P = 0.001; r = 0.304, P = 0.007)." (PMID 36726488, 2023). "Furthermore, patients with splenomegaly and generalized lymphadenopathy had high percentages of PD-L1+CXCR3+ lymphocytes." (PMID 36726488, 2023). "Many aspects of chronic HTLV-1 infection in humans were observed in this model, such as splenomegaly, proliferation of effector/memory CD4+ and CD8+ T-cells and polarization of the immune response to T-cell phenotypes associated with the expression of CXCR3 and CCR5." (PMID 34685494, 2021). "In spite of no evident splenomegaly, a 2-3-fold increase in the number of CXCR3+ CD4+ and CD8+ T cells was observed in IP-10−/− mice compared to controls." (PMID 19343215, 2009).